IL1B (interleukin 1 beta)
Diseases named in the same sentence as IL1B in open-access papers (continued):
Sharing a sentence is not in itself a finding about the gene and the disease.
spondyloarthritis (5 papers, 2009 to 2021). "In cord blood or spondyloarthropathies, abnormal Th1 and Th17 differentiation have been postulated in response to IL-1β and IL-23." (PMID 32961930, 2020). "Increased IL-1β mRNA has been found in peripheral blood profiling in individuals with spondyloarthropathy." (PMID 19900269, 2009).
staphylococcal infection (5 papers, 2015 to 2025). An infection caused by Staphylococcus. "During staphylococcal encounter with murine neutrophils or staphylococcal infection of the murine peritoneal cavity, calprotectin increases the activity of the SaeRS TCS as well as the production of proinflammatory cytokines such as IL-1β and TNF-α, resulting in higher murine mortality." (PMID 26147796, 2015).
tendinitis (5 papers, 2020 to 2025). Inflammation of a tendon, usually resulting from an overuse injury. "In addition, the PI3K signaling pathway has been shown to be inhibited by the flavonoid quercetin with a simultaneous decrease in IL-1β and IL-6 levels, as well as by resveratrol, showing the neuro- and tendinitis-protective effects following down-regulation of the PI3K signaling pathway." (PMID 35631173, 2022).
urolithiasis (5 papers, 2015 to 2024). Stone(s) within the urinary tract. "However, previous reports have focused on the frequency of polymorphisms located in IL-1RN, IL-1β, and IL-18 genes in patients with urolithiasis." (PMID 37878647, 2023). "Similarly, in the Turkish population, polymorphism analysis suggested that IL-1RN and IL-1β (−511) SNPs were associated with urolithiasis." (PMID 34440695, 2021). "The IL-1β values in our study showed that the urolithiasis group had an increased release of the cytokine when compared to the control group." (PMID 26689528, 2015).
uterine disease (5 papers, 2012 to 2025). "The ability of epithelial cells, and inability of stromal fibroblasts, to directionally secrete IL-1β has several implications for the cytokine's role in uterine disease." (PMID 30804935, 2019). "A role for the cytokine IL-1β has been widely studied in mouse and human models of inflammatory disease, with evidence of its role in bovine uterine disease emerging in recent years." (PMID 30804935, 2019). "In agreement with previous literature by us and others, significant upregulation of genes encoding the potent Interleukin-1 family of inflammatory cytokines including IL1A and IL1B were detected signifying an exacerbation of inflammation in cows which subsequently develop clinical uterine disease." (PMID 33106520, 2020). "By 21 DPP IL-1β expression in healthy animals had begun to resolve while strong expression of IL-1β was still evident in biopsy sections taken from cows diagnosed with uterine disease." (PMID 30804935, 2019). "However, according to our results, IL-1β is not a suitable diagnostic marker for uterine diseases within the first 20 days of calving." (PMID 33132596, 2020). "As both IL-1α and IL-1β have been shown to recruit different innate cells—accumulation of IL-1α correlated with the infiltration of neutrophils, and the expression of IL-1β correlated with later migration of macrophages, this could have important consequences for uterine disease pathogenesis." (PMID 33106520, 2020). "Neither the pro-inflammatory cytokine IL-1β nor the neuropeptide VIP is proposed as a suitable single test indicator of uterine involution disturbances or uterine diseases within the first 3 weeks of calving." (PMID 33132596, 2020).
VEXAS syndrome (5 papers, 2024 to 2025). An adult-onset inflammatory disease that affects only males and is caused by somatic, not germline, mutations. "Although SchS, characterized by aberrant inflammasome activation with excessive interleukin‐1β (IL‐1β) production and typically IgM clonal gammopathy, is a well‐recognized entity within this group, VEXAS syndrome, has not yet been classified as such." (PMID 40448343, 2025).
Achalasia (4 papers, 2016 to 2025). A disorder of esophageal motility characterized by the inability of the lower esophageal sphincter to relax during swallowing and by inadequate or lacking peristalsis in the lower half of the body of the esophagus. "The expression of DOK1 and DOK2 leads to the induction of IL-1β in the LES of achalasia patients, potentially leading to the esophageal motility disorder." (PMID 38792545, 2024). "The upregulation of DOK1 and DOK2 expression induces IL-1β expression in the LES of achalasia patients, which may contribute to the development of esophageal motility disorder." (PMID 38792545, 2024). "Patients with achalasia are characterized by significantly higher esophageal lymphocyte infiltration, mainly represented by CD3+CD8+ T cells and IL-1β, IFNγ, and IL-232." (PMID 27511445, 2016).
acute pyelonephritis (4 papers, 2009 to 2024). "In a previous study conducted with children diagnosed with acute pyelonephritis and lower UTIs, the diagnostic values of serum PCT and interleukin (IL)-1β levels were compared with sedimentation rate and CRP levels." (PMID 38611690, 2024). "IL-1β has also been studied to differentiate between acute pyelonephritis and lower UTI." (PMID 19707519, 2009). "Additionally, in predicting acute pyelonephritis, the sensitivities and specificities were shown to be 31.0% and 84.7% and 27.2% and 90.0% for serum PCT and IL-1β, respectively." (PMID 38611690, 2024).
African trypanosomiasis (4 papers, 2015 to 2024). "Similarly, a possible pathogenic mechanism of sleep disturbances observed in human African trypanosomiasis (HAT) patients is the upregulations of cytokines such as interleukin-1 beta (IL-1β) and tumor necrosis factor-alpha (TNF-α)." (PMID 35095888, 2021).
alcohol addiction (4 papers, 2019 to 2023). "Disulfiram is a drug employed for treating alcohol addiction, whose mechanism is based on the inhibition of pore formation by gasdermin D, allowing IL-1β and gasdermin D processing but prevents pore formation, thus preventing IL-1β release and pyroptosis." (PMID 35052711, 2021). "Alcohol addiction can lead to endotoxemia and the increased secretion of pro-inflammatory cytokines, like interleukin-1β (IL-1β) and interleukin-6 (IL-6), which can alter various signaling pathways and cause damage in the central nervous system and other organs." (PMID 38275640, 2023). "However, to our knowledge, there are no studies that focus on the genetic variability of PON1, SOD2, GPX1, IL1B, IL6, interleukin 6 receptor (IL6R), and miR146a related to the risk of alcohol addiction, and patients’ comorbid psychosymptomatology." (PMID 38275640, 2023). "Thus, we focused on the role of PON1 rs705379, rs705381, rs854560, and rs662, SOD2 rs4880, GPX1 rs1050450, IL1B rs1143623, rs16944, and rs1071676, IL6 rs1800795, IL6R rs2228145, and miR146a rs2910164 in alcohol addiction, and patients’ comorbid psychosymptomatology." (PMID 38275640, 2023).
anorexia nervosa (4 papers, 2016 to 2023). A disorder most often seen in adolescent females characterized by a refusal to maintain a minimally normal body weight, an intense fear of gaining weight, a disturbance in body image, and, in postmenarcheal females, the development of amenorrhea. "In patients with anorexia nervosa, an increase in pro-inflammatory cytokines, such as interleukin-1β (IL-1β), tumor necrosis factor-α (TNF-α), and interleukin-6 (IL-6), have also been reported." (PMID 35215322, 2022).
antiphospholipid syndrome (4 papers, 2019 to 2025). A disorder caused by the presence of autoantibodies directed against phospholipids, causing a hypercoaguable state, which may result in blood clots, stroke, heart attack, and in women, significant pregnancy-related complications, including miscarriage and still birth. "The activation of inflammasome as well as secretion of IL-1β seem to increase inflammation, which has been proposed as one of the causes of RPL in the antiphospholipid syndrome." (PMID 38139443, 2023).
antisynthetase syndrome (4 papers, 2020 to 2024). Antisynthetase (AS) syndrome is a clinically heterogeneous form of idiopathic inflammatory myopathy characterized by myositis, arthralgia, Raynaud phenomenon, mechanic hands, interstitial lung disease (ILD), and serum autoantibodies to aminoacyl transfer RNA synthetases (anti-ARS). "It is reported that single nucleotide polymorphisms (SNPs) of IL-1β, rs16944, and rs1143627, are related to IL-1β serum levels in patients of febrile seizure and antisynthetase syndrome." (PMID 35464987, 2022). "Notably, higher IL-1β levels were associated with a GA at −511 [rs16944] in Mexican patients with antisynthetase syndrome suggesting a correspondence between the SNP and serum IL-1β levels but SNP - IL-1β validation studies in adults are rare." (PMID 39055623, 2024).
aortic atherosclerosis (4 papers, 2019 to 2023). A atherosclerosis that involves the aorta. "COL6A1 immunization in female mice interrupted this pathway with a tolerance-like response of decreased CD8+ T cell cytolytic activity and reduced IL-1β expression with decreased aortic atherosclerosis." (PMID 32373127, 2020). "After aortic chemerin gene was inhibited by adenovirus, aortic atherosclerosis induced by high-fat diet was significantly meliorated, serum levels of TNF-α and IL-1β decreased, mRNA and protein levels of NF-κBp65, PCNA, p-p38-MAPK, p-JNK, and p-ERK 1/2 decreased simultaneously." (PMID 31781638, 2019).
Arterial thrombosis (4 papers, 2015 to 2023). The formation of a blood clot inside an artery. "A remarkable reduction in αIIbβ3 signaling transduction was observed together with the the release of IL-1β in NLRP3 deficient platelets, suggesting NLRP3 inflammasome contribute to the hemostasis and arterial thrombosis with the mediation of IL-1β release and αIIbβ3 signaling." (PMID 36204568, 2022). "IL-1β accumulation in arterial thrombosis in vivo precedes mononuclear leukocytes incorporation to the clot and is not affected by transcription inhibition, which dampens IL-1β synthesis in leukocytes but not in platelets." (PMID 25814789, 2015).
Atherosclerotic lesion (4 papers, 2019 to 2025). A lesion associated with atherosclerosis, a multifactorial and multipart progressive disease manifested by the focal development within the arterial wall of lesions, that ranges from the development of a fatty streak, plaque progression, and plaque disruption. "Results showed that LECT2 reduced total cholesterol and low-density lipoprotein concentrations in serum and inhibited the development of atherosclerotic lesions, accompanied by reductions in inflammatory cytokines and lower MCP-1, MMP-1, TNF-α, IL-8, and IL-1β mRNA abundance." (PMID 31310065, 2019).
autoimmune encephalitis (4 papers, 2022 to 2025). Inflammation of the brain secondary to an immune response triggered by the body itself. "Our study provided a clinically relevant model of anti-NMDAR encephalitis and emphasized blocking Il-1β signaling as a promising strategy to ameliorate autoimmune encephalitis." (PMID 37443034, 2023). "Studies in patients with NMDAR antibody-associated autoimmune encephalitis have shown an increase in serum IL-2 and CSF IL-6, IL-17, CXCL-10, and IL-1β." (PMID 36048783, 2022). "AE at the time of diagnosis when Plasma IL-1β and IL-10 ratio of mean values in leucine-rich glioma inactivated 1 autoimmune encephalitis (LGI1 AE) vs. non-inflammatory controls." (PMID 40470500, 2025).
bronchitis (4 papers, 2013 to 2024). An acute or chronic inflammatory process affecting the bronchi. "Uric acid could trigger ROS production and stimulated the release of NLRP3 inflammasome, which occurred following childhood wheezing or bronchitis and was related to IL-1β generation." (PMID 36059973, 2022).
calcinosis (4 papers, 2010 to 2025). Deposition of calcium in the tissues. "Cytokines such as IL-6, IL-1β, TNF-α, IL-1β, and IL-6 were also detected in serum, suggesting the role of activated macrophages in JDM-associated calcinosis." (PMID 32550037, 2020). "Research on calcinosis lesions reveals the presence of TNF, interleukin-1 beta, and anti-inflammatory cytokines in the calcium milk extracted from these lesions." (PMID 38166943, 2024).
central nervous system infection (4 papers, 2022 to 2023). "Previous studies on Atlantic hagfish, rat, and IL-1β-converting enzyme-deficient mice revealed the aggravative effect of IL-1β on the primary damage induced by central nervous system infection." (PMID 36078068, 2022). "Infections of the central nervous system, cell death, brain injury, and neurodegenerative disease all rely on IL-1β and IL-18." (PMID 36429017, 2022). "Immunohistochemistry of post-mortem brain sections of CM cases of Ghanian children showed strong intravascular IL-1β staining which was absent in cases without central nervous system infections." (PMID 37141324, 2023).
cerebral small vessel disease (4 papers, 2021 to 2025). Cerebral small vessel disease is the term currently used to pathological processes that affect the brain parenchymal circulation (arterioles, capillaries, and veins). "A clinical study suggested that inflammasome-related inflammatory factor IL-1β is correlative with cerebral small vessel disease patients." (PMID 37533068, 2023). "Cerebral small vessel disease causes blood–brain barrier (BBB) functional damage, chronic inflammation such as the increased IL‐1β and TNF‐α expression, and leukocyte infiltration, leading to the development of neuron and oligodendrocyte injury." (PMID 34586752, 2021). "Cerebral small vessel disease (CSVD) may benefit from anti-inflammatory therapy, as age-related inflammation—mediators such as TNF, caspase-1, IL-1β, and the NLRP3 inflammasome—is considered a risk factor." (PMID 40017533, 2025). "A study demonstrated that increased IL‐1β and TNF‐α expressions were observed in the hippocampus of a rat cerebral small vessel disease model." (PMID 34586752, 2021).
colonic disease (4 papers, 2018 to 2025). "IBD is a colon disorder associated with increased levels of proinflammatory cytokines, including tumor necrosis factor-a, interleukin (IL)-1b, IL-2, and IL-6." (PMID 39979878, 2025). "As NO is regarded as a biomarker of inflammatory activity in colonic disease, immunoreactivity of iNOS and IL-1β (e.g., as by promoting iNOS expression) was hypothesized to predict CAC prognosis." (PMID 38187473, 2023). "Combined these results indicate IL-1β may have a role in colonic disease states including dysmotility, diarrhoea and lower abdominal pain." (PMID 29933379, 2018).
complex regional pain syndrome (4 papers, 2020 to 2025). A chronic pain syndrome characterized by a disproportionate spontaneous or stimulus-induced pain, accompanied by a variably mixed myriad of autonomic and motor disorders including symptoms such as swelling, allodynia, skin blood supply and trophic disturbances. "IL-1β levels are increased in the CSF of patients with complex regional pain syndrome and with thoracic disc herniation." (PMID 35295524, 2021).
coronary aneurysm (4 papers, 2018 to 2025). Abnormal balloon- or sac-like dilatation in the wall of coronary vessels. "Type I interferon augments TNF- and IL-1β-mediated inflammatory responses and is elevated in KD with coronary artery aneurysms." (PMID 41394864, 2025). "While KD involves chronic endothelial activation and a significant risk of coronary aneurysms, MIS-C is characterized by acute elevations in proinflammatory cytokines—such as IL-6, IL-1β, and TNF-α—leading to systemic inflammation and transient cardiac dysfunction." (PMID 40332089, 2025).
coronary artery calcification (4 papers, 2010 to 2025). Calcification of the coronary artery, used as a measure of coronary atherosclerosis, a risk factor for myocardial infarction. "In the nondominant hand it was associated with higher systolic blood pressure, IL-1β, and coronary artery calcification (CAC)." (PMID 39883521, 2025). "Although inflammatory markers, such as CRP, IL-1β, and IL-6, are associated with cardiovascular diseases, OPG is a unique biomarker in that elevated levels have independently correlated with progression of coronary artery calcification." (PMID 20307322, 2010).
crystal arthritis (4 papers, 2006 to 2021). "OM-3 CA has a broadly efficacious anti-inflammatory effect with a strong exposure–response relationship that could be beneficial in prevention and treatment of crystal arthritis, with potential applications in other IL-1β-mediated diseases." (PMID 29352206, 2018).
diabetic encephalopathy (4 papers, 2019 to 2026). A brain disease that is characterized by functional impairment of cognition, cerebral signal conduction, neurotransmission and synaptic plasticity, and underlying structural pathology associated with diabetes. "Diabetic encephalopathy was characterized by robust neuroinflammatory activation, with pro-inflammatory cytokines significantly elevated: TNF-α (4.7-fold), IL-6 (3.8-fold), IL-1β (3.2-fold), and IFN-γ (2.9-fold) compared to controls." (PMID 40723442, 2025).
Dyskinesia (4 papers, 2020 to 2024). A movement disorder which consists of effects including diminished voluntary movements and the presence of involuntary movements. "Furthermore, animals treated with candesartan along with l-dopa were characterized by lower levels of VEGF, IL-1β, and less severe dyskinesia compared to animals receiving only l-dopa." (PMID 33802165, 2021). "L-DOPA is responsible of inducing dyskinesia (LID) in animals with partial lesion of SN, increasing plasmatic levels of TNFα and IL-1β, and treatment with CBD + CPZ lowered TNFα levels and ameliorated the LID and inflammatory prognostic of the model." (PMID 39533977, 2024). "In animals with dyskinesia, higher concentrations of VEGF and IL-1β within striatum and substantia nigra were found." (PMID 33802165, 2021). "We wished to determine whether the treatment with CPZ + CBD, reported being effective against dyskinesia, also had the capacity of reducing levels of TNF-α and IL-1β in the dorsal striatum of 6-OHDA-lesioned mice treated with L-DOPA." (PMID 33510643, 2020).
dysthymia (4 papers, 2011 to 2024). "In addition, high levels of IL-1β and decreased TNF-α were observed in children and adolescents with dysthymia." (PMID 30662368, 2018).
Fabry disease (4 papers, 2019 to 2025). Fabry disease (FD) is a progressive, inherited, multisystemic lysosomal storage disease characterized by specific neurological, cutaneous, renal, cardiovascular, cochleo-vestibular and cerebrovascular manifestations. "In this study, we were able to show that PPS reduces the secretion of TNFα and IL1β in a chemical in vitro model of Fabry disease to control levels." (PMID 31150494, 2019). "Patients with Fabry disease also demonstrate an increase in T cell subsets and increased circulatory levels of pro-inflammatory cytokines, such as TNFα, IFNγ, IL1α, IL1β, IL6, and IL17." (PMID 39596318, 2024). "Serum, plasma, PBMCs, and several of the immune cells that include MOs, DCs, and NK cells have shown massive production of pro-inflammatory cytokines (e.g., IFNγ, TNF α, IL1β, and IL6) in patients with Fabry disease." (PMID 37189685, 2023).
fasciitis (4 papers, 2017 to 2024). Inflammation process in fascia. "Interleukin-1β (IL-1β) and interleukin-8 (IL-8) levels were elevated in vitro, potentially contributing to the very high neutrophil counts observed during fasciitis episodes." (PMID 36892687, 2023). "In fasciitis patients with a known underlying truncating NFKB1 mutation, anti-inflammatory therapies, including glucocorticoids and/or IL-1β targeting therapies or JAK inhibitors, could be beneficial in reducing excessive inflammation and the need for surgical revisions and amputations." (PMID 38593810, 2024).